SLC10A4 (solute carrier family 10 member 4)
Description:
No significant bile acid transporter activity could be measured despite its similarity to bile acid:sodium symporters.
Synonyms: MGC29802; P4
Tractability: Antibody: UniProt places it where antibodies can reach, with high confidence; its Gene Ontology location is reachable by antibodies, with high confidence; UniProt predicts a signal peptide or a membrane-spanning region. PROTAC: ubiquitination databases record sites on it.
Gene: Protein-coding gene on chromosome 4 (48,483,343 to 48,489,526, forward strand). Ensembl gene ENSG00000145248.
Subcellular location: Cell membrane
Gene Ontology:
Molecular function: bile acid:sodium symporter activity; protein binding
Biological process: bile acid and bile salt transport
Cellular component: plasma membrane; membrane
Genetic constraint (gnomAD): Loss-of-function variants: 17 observed, 21.61 expected, observed/expected ratio (o/e) 0.79, 90% interval 0.54 to 1.18. The upper end of that interval is the gene's LOEUF score, 1.18, which puts it in group 5 of 6, group 1 being the genes least tolerant of losing a copy. Missense variants: 493 observed, 482.11 expected, observed/expected ratio (o/e) 1.02, 90% interval 0.95 to 1.1. Synonymous variants: 230 observed, 211.04 expected, observed/expected ratio (o/e) 1.09, 90% interval 0.98 to 1.22.
Homologues: Orthologues: chimpanzee SLC10A4 (99% identical), macaque SLC10A4 (97% identical), rat Slc10a4 (87% identical), rabbit SLC10A4 (87% identical), pig SLC10A4 (86% identical), guinea pig SLC10A4 (79% identical), tropical clawed frog slc10a4 (59% identical), zebrafish slc10a4 (58% identical), dog SLC10A4 (51% identical), mouse Slc10a4-ps (30% identical). Paralogues in human: SLC10A1 (27% identical), SLC10A2 (26% identical), SLC10A6 (26% identical), SLC10A3 (20% identical), SLC10A5 (20% identical).
Diseases named in the same sentence as SLC10A4 in open-access papers:
SLC10A4 is named in the same sentence as 7 diseases in open-access papers, as found by Europe PMC text mining. Sharing a sentence is not in itself a finding about the gene and the disease. The quoted sentences say what the papers report.
allergies (1 paper, 2017). "Thus, SLC10A4 is a potential novel drug target for mast cell-related diseases such as allergies." (PMID 28439090, 2017).
Alzheimer disease (1 paper, 2020). A progressive, neurodegenerative disease characterized by loss of function and death of nerve cells in several areas of the brain leading to loss of cognitive function such as memory and language. "The related SLC10A4 gene encodes a synaptic vesicle protein also involved in Alzheimer disease." (PMID 32410960, 2020).
neuroblastoma (1 paper, 2015). Neuroblastoma (NB) is the most common solid, extracranial childhood tumor. "Therefore, we analyzed SLC10A4 expression in the human neuroblastoma cell line SH-SY5Y as well as in the mouse cell line CAD (Cath.a-differentiated neuronal cells, originating from the locus coeruleus in the brainstem) with different SLC10A4-directed antibodies." (PMID 26084360, 2015).
status epilepticus (1 paper, 2015). Status epilepticus is defined as a continuous seizure lasting more than 30 min, or two or more seizures without full recovery of consciousness between any of them. "Injection of the cholinergic agonist pilocarpin induced status epilepticus earlier and more often in the Slc10a4 knockout mice compared with the wild type mice, suggesting that SLC10A4 may suppress epileptiform activity." (PMID 26084360, 2015).
cancer (3 papers, 2017 to 2020). A tumor composed of atypical neoplastic, often pleomorphic cells that invade other tissues. "Interestingly, 5 out of the top 10 hub genes in the network are cancer genes, including ELF3, SLC10A4, ANXA9, DEFB118, KRT8." (PMID 32064261, 2020). "Despite this, SLAIN2 strongly stimulated processive MT polymerization in interphase cells and, in a murine cancer model, it is essential for mesenchymal cell invasion in 3D culture while, in rats, SLC10A4 is expressed by cholinergic neurons even if it is not reported as choline transporter." (PMID 32784482, 2020).
SLC10A4 also shares sentences with these, for which no sentence is quoted: intestinal tumor (1 paper); medulloblastoma (1).